CFAP144 (cilia and flagella associated protein 144)
Description:
Microtubule inner protein (MIP) part of the dynein-decorated doublet microtubules (DMTs) in cilia axoneme, which is required for motile cilia beating.
Synonyms: FAM183A; LOC440585; hCG23177
Tractability: Small molecule: a structure with a bound ligand is known.
Gene: Protein-coding gene on chromosome 1 (43,145,153 to 43,156,396, forward strand). Ensembl gene ENSG00000186973.
Subcellular location: Cytoplasm, cytoskeleton, cilium axoneme; Cytoplasm, cytoskeleton, flagellum axoneme
Subcellular location (Human Protein Atlas): Mid piece
Gene Ontology:
Molecular function: microtubule binding
Biological process: flagellated sperm motility
Cellular component: axonemal microtubule; axonemal B tubule inner sheath; ciliary base; sperm flagellum; axoneme
Genetic constraint (gnomAD): Loss-of-function variants: 11 observed, 15.92 expected, observed/expected ratio (o/e) 0.69, 90% interval 0.43 to 1.14. The upper end of that interval is the gene's LOEUF score, 1.14, which puts it in group 5 of 6, group 1 being the genes least tolerant of losing a copy. Missense variants: 146 observed, 167.53 expected, observed/expected ratio (o/e) 0.87, 90% interval 0.76 to 1. Synonymous variants: 57 observed, 60.3 expected, observed/expected ratio (o/e) 0.95, 90% interval 0.76 to 1.18.
Homologues: Orthologues: chimpanzee CFAP144 (100% identical), macaque CFAP144 (94% identical), rabbit CFAP144 (84% identical), guinea pig CFAP144 (81% identical), mouse Cfap144 (79% identical), rat Cfap144 (79% identical), tropical clawed frog cfap144 (49% identical), zebrafish cfap144 (45% identical). Paralogues in human: CFAP144P1 (84% identical).
Diseases named in the same sentence as CFAP144 in open-access papers:
CFAP144 is named in the same sentence as 4 diseases in open-access papers, as found by Europe PMC text mining. Sharing a sentence is not in itself a finding about the gene and the disease.
CFAP144 shares sentences with these, for which no sentence is quoted: tumor (2 papers); breast carcinoma (1); Intellectual disability (1); lymph node metastasis (1).